PDGFRA (platelet derived growth factor receptor alpha)
Diseases named in the same sentence as PDGFRA in open-access papers (continued):
Sharing a sentence is not in itself a finding about the gene and the disease.
glioma (continued). "This abundant expression leads to the stimulation of the glial tumour cells by the tandem PDGF/PDGFR, especially PDGFRA." (PMID 23998913, 2013). "We also found the total numbers of sole activators of FOXM1, PDGFRA, OPN, CYCLIN_D, CYCLIN_E, BMI, SNAI1, JAGGED2, SFRP were increased in Glioma scenario as compared to the canonical HH pathway." (PMID 23935937, 2013). "Immunohistochemical staining results for PDGFRA and FGF2 in glioma samples - Predominant staining intensity in each sample." (PMID 23630597, 2013). "Our analyses on hallmark alterations in glioma genome show that LOH of 1p and 19q is more frequent in PDGFRA-high gliomas, and that EGFR amplification is more frequent in PDGFRA-low and PDGFRA-intermediate gliomas." (PMID 23630597, 2013). "In “secondary glioma pathway”, gains of PDGFA (1 in LGG and 2 in HGG), PDGFRA (2 in LGG and 2 in HGG) and CDK4 (1 in LGG and 2 in HGG) and RB1 (2 in HGG), and losses of RB1 (1 in LGG and 2 in HGG) are also identified." (PMID 23451178, 2013). "In both data sets, the patterns of FGF2 expression were similar to those of PDGFRA expression; FGF2 expression was significantly enriched in low-grade gliomas, compared to high-grade gliomas (P<0.001, t test)." (PMID 23630597, 2013). "Moreover, the gene expression profile of group 1 DIPG was significantly enriched with genes describing the signature of PDGFRA amplified gliomas supporting the hypothesis that PDGFRA amplification is associated with a robust gene expression profile across tumor location and patient's age." (PMID 22389665, 2012). "Deregulation of the PI3K/AKT/mTOR signaling pathway and hyperactivation of receptor-tyrosine kinases (e.g., PDGFRα and EGFR) are frequently observed in gliomas." (PMID 21209724, 2011). "Given that PDGFRA is a transmembrane tyrosine kinase receptor and that these receptors have been shown to be amenable to exploitation as therapeutic targets, it seems reasonable to hypothesise that PDGFRA may constitute a potential target for anticancer therapy in gliomas." (PMID 19707201, 2009). "Six low-grade and 17 high-grade glioma specimens were flow-cytometrically analyzed for markers characteristics of stem cells (CD133); glial progenitors (PDGFRα, A2B5, O4, and CD44); and late oligodendrocyte progenitors (O1)." (PMID 18398462, 2008). "Although previous studies suggested glioma expression of oligodendrocyte progenitor cell antigen NG2 and PDGFRα, and transcription factor Olig1/2, the lineage commitment and the stage of differentiation blockage of glioma cells are not clarified." (PMID 18398462, 2008). "We have analyzed the expression of PDGFRα, A2B5, O4 and CD44 as surface markers for glial precursor cells, and CD133 for stem cells on freshly prepared glioma cells using flow cytometry." (PMID 18398462, 2008). "Platelet-derived growth factor receptor alpha (PDGFRA) has emerged as a pivotal oncogenic driver in gliomas, not only promoting cellular proliferation and angiogenesis but critically orchestrating complex immune evasion mechanisms." (PMID 41847712, 2026). "Consistent with this idea, IDH-mutant gliomas display DNA hypermethylation at insulator protein CTCF binding sites, resulting in upregulation, although not mutation, of proto-oncogene PDGFRA." (PMID 40156071, 2025). "In glioma, PDGFB and its cognate receptor, PDGFRA, are detected in mIDH tumors, whereas, in the non-tumor human brain, PDGFB is minimally expressed by microglia and vascular cells, and PDGFRA is highly expressed by OPCs." (PMID 40060572, 2025). "Hence, rat glioma 101.8 is potentially a quite reliable preclinical model to evaluate the anti-tumor efficacy of SOX2-, OLIG1/2-, and PDGFRA-targeting therapy approaches." (PMID 41009560, 2025). "In LTS, myxoid glioneuronal tumor, PDGFRA-mutant was seen as re-assigned LTS entity which clustered in the predominantly STS cluster A. In line, clustering showed a distinct methylation profile from IDH-mutant glioma as comparison group for LTS." (PMID 39954095, 2025).
glioma (continued). "Pathway enrichment analysis identified four essential genes—PDGFA (ligand), PDGFRA (receptor), CREB1 (TF), and PLAT (target gene)—involved in the Receptor Tyrosine Kinases (RTK) signaling pathway, which plays a pivotal role in glioma progression from grade III to grade IV." (PMID 39606019, 2024). "In addition, through modifying platelet derived growth factor receptor alpha (PDGFRA)-xCT, elevated circCDK14 notably reduces gliomas' sensitivity to ferroptosis." (PMID 39309434, 2024). "Our results were consistent with the clinical observations that, single inhibition of PDGFRA by dasatinib had failed to improve the clinical outcomes of glioma, even in glioma patients with PDGFRA amplifications or over‐expressions." (PMID 36043552, 2023). "So, compared with PDGFRA, IGFBP7 was a more suitable prognostic and therapeutic target of glioma." (PMID 36043552, 2023). "We also performed IHC staining, utilizing PDGFRA antibody (OPC-like marker), EGFR antibody (AC-like marker) and HIF-1A antibody (MES-like marker) and confirmed the specific cell states are enriched in distinctive proteomic subsets of gliomas." (PMID 36720864, 2023). "BCLAF1 acts in a positive feedback loop enhancing PDGFRa and EGFR signaling in high-grade glioma." (PMID 37579831, 2023). "In particular, EGFR (22/26) and CDK4 (6/8) mutations were more present in patients with GBM than those with other gliomas, whereas PDGFRA CNVs were present only in patients with GBM (3/3; data not shown)." (PMID 36959606, 2023). "Despite the known intratumoral heterogeneity of its somatic alterations, PDGFRA is considered a therapeutic target based on abated growth upon treatment with PDGFRA inhibitors and reduced viability after genetic knockout of PDGFRA in models of DMG-H3 K27-a glioma." (PMID 35642016, 2022). "Thus, the distribution feature of PDGFRA and EPHA2 implied that the two proteins were related with malignant phenotype of glioma." (PMID 35105853, 2022). "GOLM1 promotes HCC, glioma and prostate cancer proliferation and growth through the regulation of the EGFR/PDGFRα/RTK signaling pathway, thus resulting in the activation of PI3K/AKT/mTOR signaling cascade and in the positive feedback loop, already described in the previous section." (PMID 35805075, 2022). "Targeting PDGFRA by tyrosine kinase inhibitors (TKIs) or antibodies showed promising antitumor effects in patients with various PDGFR-driven extracranial tumors and pre-clinical models of gliomas." (PMID 35109850, 2022). "Based on the cell markers, cluster 0 overexpressing PDGFRA and cluster 2 overexpressing EGFR could be annotated as glioma cells." (PMID 36276141, 2022). "Agents targeting PDGFRA‐alterations, such as dasatinib, failed to exert any effect in clinical trials in glioma patients, but there are some promising data regarding the potential efficacy of combinations with mTOR inhibitors." (PMID 35545820, 2022). "Similarly, miR-34a regulates PDGFRA and PAX8, two genes which are known to be involved in childhood CNS tumors, as especially PDGFRA has been studied for its role in gliomas." (PMID 34771655, 2021).
glioma (continued). "Flavahan and colleagues demonstrated that human IDH mutant gliomas exhibit hypermethylation at CTCF-binding sites, resulting in alteration 3D structure genome-wide and activation of the oncogene PDGFRA by allowing a constitutive enhancer to interact aberrantly with PDGFRA promoter." (PMID 34638453, 2021). "Despite the importance of PDGFRA signaling for OPC development, and its dysregulation in gliomas, the cellular and molecular consequences of amplified PDGFRA signaling in OPCs are unknown." (PMID 34480532, 2021). "PDGF receptor-α (PDGFRα) is an RTK that is commonly overexpressed and amplified in gliomas." (PMID 34064863, 2021). "Moreover, the ctDNAs in the metastatic brain tumors included ALK and MDM2, and glioma-related ctDNAs included 1p/19q and MDM2 followed by frequencies of ERBB2, IDH1, CDKN2A, CDK4, PDGFRA, CCNE1, MET." (PMID 32973641, 2020). "Glioma-related ctDNAs included 1p/19q, MDM2, ERBB2, IDH1, CDKN2A, CDK4, PDGFRA, CCNE1, MET." (PMID 32973641, 2020). "The amplification and activation of EGFR, platelet derived growth factor receptor α (PDGFRα), and mesenchymal-epithelial transition factor (MET) promote the proliferation and invasion of glioma cells and are correlated with recurrence and therapeutic resistance." (PMID 31245283, 2019). "The human glioma gene expression data from 155 primary GBM tumors in The Cancer Genome Atlas (TCGA) Data Portal was analyzed and 65 tumors were selected for the DEG comparison based on elevated (≥10 log2a change) PDGFRA gene expression." (PMID 29352201, 2018). "One such mechanism in glioma may be through methylation-induced disruption of a CCCTC-binding factor (CTCF) binding site, resulting in aberrant activation of platelet-derived growth factor receptor alpha (PDGRFA)." (PMID 29616301, 2018). "Diffuse gliomas expressed NG2/CSPG4, PDGFRα, and Olig2, that are characteristic of OPCs." (PMID 30213051, 2018). "Gliomas may contain subpopulations of cells carrying mutually exclusive amplifications of oncogenes EGFR and PDGFRα." (PMID 28074274, 2017). "Previous large-scale characterizations of PDGFRA alterations in glioma have not reported this, either because they have focused on adults patients or amplification (by FISH) alone." (PMID 27582545, 2016). "To test this, we evaluated regorafenib in combination with radiotherapy against the PDGFRA non-amplified pediatric glioma NEM14." (PMID 26599335, 2015). "In addition to the EGFR signaling axis, PDGFRα and its ligands, PDGF-A and PDGF-B, are represented in gliomas, especially in HGG." (PMID 25147764, 2014). "Furthermore, OPCs and pericytes express PDGFRα and PDGFRβ, respectively, and it has been shown that PDGF is a strong inducer of glioma." (PMID 24465393, 2014). "CDK4 and PDGFRA amplification were rare in GII/IIIs overall, suggesting that these events may play a role in the progression of a lower grade to a higher grade glioma." (PMID 24614622, 2014). "Recently, it has been reported that tyrosine-protein phosphatase non-receptor type 11 (SHP-2) and PI3K mediate PDGFRα-promoted glioma tumor growth and invasion." (PMID 25380967, 2014). "Our findings show that also in the absence of acute ligand stimulation, PDGFRA molecules exhibit dynamic trafficking in glioma cells, and this trafficking process is regulated by MEK-ERK signaling." (PMID 24489888, 2014).
glioma (continued). "Cdc42 activation has also been demonstrated alongside Rac1 activation in GB cells downstream of PDGFRα association with SHP-2 non-receptor protein tyrosine phosphatase and Dynamin 2 (Dyn2) to promote glioma cell migration." (PMID 24109588, 2013). "Astrocytic gliomas of various grades have been shown to overexpress platelet-derived growth factor receptor alpha (PDGFR-α), whereas both PDGF-AA and PDGF-BB have been consistently found in high grade gliomas (grade III and IV) only, generating autocrine stimulation." (PMID 22931209, 2012). "Nevertheless, we anticipate that other important miR-34a targets remain to be identified, particularly given that selective PDGFRA knockdown does not fully recapitulate the effects of miR-34a on cell proliferation in proneural glioma cells." (PMID 22479456, 2012). "Taken together, our data support the existence of reciprocal negative feedback regulation involving miR-34 and PDGFRA expression in proneural gliomas and, as such, identify a subtype specific therapeutic potential for miR-34a." (PMID 22479456, 2012). "Irrespective of the grade and morphological diagnosis of gliomas, glioma cells concomitantly expressed PDGFRα, A2B5, O4, CD44 and GFAP." (PMID 18398462, 2008). "However, the prognosis of PDGFRA and IGFBP7 in glioma is unclear." (PMID 36043552, 2023). "IGFBP7 but not PDGFRA served an ideal prognostic marker and therapeutic target of glioma." (PMID 36043552, 2023). "However, we were not able to ascertain the specific role decreased PDGFRα activation played in the cytotoxic and antiproliferative responses of our glioma cells to JQ1." (PMID 35467128, 2022). "The invasion-promoting effects of PDGF is also supported in other non-nervous system tumor types and argues that PDGFRA signaling in glioma may serve more than just a growth factor/proliferation signal." (PMID 36182941, 2022). "Notably, treatment of IDH mutant glioma cells with a demethylation agent reduced methylation at CTCF binding sites and partially restored CTCF binding and insulator function, which in turn restored PDGFRA expression." (PMID 34638453, 2021). "In addition to GBM, co-expression of HIF1α and PDGFRα proteins was also observed in other types of gliomas, but not in medulloblastoma or adjacent normal brain tissues (ANB)." (PMID 34470658, 2021). "Importantly, our fully annotated cohort displays a wide variety of genetic features not recapitulated in other models (e.g., EGFR and PDGFRA amplification), thus reflecting the wide interpatient heterogeneity of high-grade gliomas." (PMID 33009951, 2020). "Besides glioblastoma, amplified PDGFRA and EGFR may also occur in lower-grade gliomas and in their recurrent tumors." (PMID 33081688, 2020). "Interestingly, interaction of CSPG4 with PDGFRA has been shown to promote oligodendrocyte progenitor cells proliferation in response to PDGF43 and a HS modification enzyme, SULF2, is also able to mediate PDGFRA activity in glioma cells." (PMID 32019907, 2020). "In this study, some important glioma-related genes were not differentially expressed in PDGFRA-overexpressing canine gliomas, including HIF1-α, CTLA4, DLL3, and TNFRSF12A, important mediators of angiogenesis, immune evasion, self-renewal, and invasion in the tumor microenvironment." (PMID 29352201, 2018). "We observed constitutive cholesterol synthesis in multiple glioma tumor sphere lines harboring a variety of alterations in this pathway, including both EGFR and PDGFRA amplification and PTEN deletion, suggesting that cholesterol synthesis inhibition might be useful across a wide genomic spectrum." (PMID 28118603, 2017).
glioma (continued). "The IGRG93 glioma carries a PDGFRA gene amplification and was included to sustain our hypothesis although the model derived from an adult glioma and no pediatric PDGFRA amplified model was available." (PMID 26599335, 2015). "PDGFRA amplification has recently been shown to be associated with a poor prognosis in IDH1 mutant GBM and have a negative prognostic value in Grade III gliomas." (PMID 24716189, 2014). "Furthermore, U0126 treatment in glioma cells induced an initial inhibition of ERK1/2 phosphorylation, followed by up-regulated ERK1/2 phosphorylation concomitant with diminished surface expression of PDGFRA." (PMID 24489888, 2014). "However, the mean fluorescence intensity of PDGFRA in the whole cells was not significantly different between the glioma tissues with low or high surface PDGFRA tissues." (PMID 24489888, 2014). "Another subset of gliomas, the PDGFR subclass account for 25-30% of GBM, and is characterized by dysregulation of PDGFR activity, which in some cases is due to amplification and rearrangements of the PDGFRα gene locus, and in others to overexpression of the PDGF ligands." (PMID 25380967, 2014). "Both the variations in the extent of surface expression of PDGFRA in glioma cells from different patients, as well as its regulation by MEK-ERK activity following U0126 treatment suggest that the PDGFRA spatial distribution could be regulated by cell signaling." (PMID 24489888, 2014). "Furthermore, NSCs of adult brain SVZ were shown to express PDGFRA, which is physiologically required for oligodendrogenesis; these cells respond to PDGF treatment by a block in neurogenesis and hyperplasia resembling early stages of glioma oncogenesis." (PMID 23998913, 2013). "FGF2 also induced PDGFRA expression in glioma cells with low or non-detectable PDGFRA expression." (PMID 23630597, 2013). "Thus, FGF2-dependent PDGFRA expression as observed in our study is likely an indirect effect; FGF2-dependent PDGFRA expression is probably applicable only to a specific subset of gliomas." (PMID 23630597, 2013). "Since gliomas with large areas of recruited cells did not express PDGFRα, we investigated whether recruited cells became independent of hPDGFb signaling during glioma progression." (PMID 21754979, 2011). "However, it cannot be excluded that A2B5+CD44+GFAP+ glioma cells without detectable PDGFRα and O4 expression (e.g.: case #9) actually represent the expansion of ARP-like cells." (PMID 18398462, 2008). "While this vector was not robust at glioma initiation (<10% incidence), injections of RCAS-RSR and RCAS-Cre into Ntv-a Ink4a/Arf-/-Ptenfl/fl mice could give rise to high-grade gliomas that did not express PDGFRα and contained regions of proliferating cells that did not express mRFP." (PMID 21754979, 2011). "While examining human glioma scRNA-seq datasets, we found that expression of PDGFB was largely absent from tumor cells, which were frequently PDGFRA+ in mIDH tumors." (PMID 40060572, 2025). "In lower grade glioma (LGG), PDGFRA over‐expression was not correlated with the unfavorable prognosis of LGG, while, IGFBP7 was a prognostic biomarker of LGG." (PMID 36043552, 2023). "No statistical survival advantage was observed with EGFR nor with PDGFRA transcripts despite the distinct differences at mRNA and protein levels between IDH-wildtype and IDH-mutant gliomas." (PMID 27852048, 2017). "Using primary-derived HCMV negative glioma stem-like cells (GSC, line 4121), we found that HCMV gB induced activation of the AKT pathway via phosphorylation of PDGFRα." (PMID 24658280, 2014).